CD4 (CD4 molecule)
Diseases named in the same sentence as CD4 in open-access papers (continued):
Sharing a sentence is not in itself a finding about the gene and the disease.
myocarditis (continued). "Next-generation sequencing of TCRs in the heart of two autopsied patients with fulminant ICI myocarditis revealed that CD4+ and CD8+ T-cell clones in the myocardium were identical to those in tumors." (PMID 33997442, 2021). "Four of five patients with myocarditis exhibited a Th1/Th2 imbalance favoring a pronounced inflammatory Th1, Th1/Th17, and Th17 CD4 memory T-cell response." (PMID 34686542, 2021). "Various CD4+ T cell populations contribute to myocarditis and to regulation of CD8+ T cell activity." (PMID 34696354, 2021). "In line with the cytokine/chemokine profile, four of five patients with myocarditis evaluated by mass cytometry exhibited a Th1/Th2 imbalance that favored a pronounced inflammatory Th1, Th1/Th17 and Th17 CD4 memory T-cell response." (PMID 34686542, 2021). "Despite the reduced mortality, CD4 KO mice (which are unable to mount normal helper-T-cell responses) had increased evidence of myocarditis at one week following CVB infection." (PMID 34696354, 2021). "Overt lymphocytic myocarditis was evident in one case (n°314), and single or multiple foci of localized myocarditis characterized two additional samples (n°354, 262), with different predominance of CD4, CD8 and CD16 lymphocytes." (PMID 34282465, 2021). "In our chronic myocarditis model, CD4+ T cells produced large amounts of IFN-γ and IL-17 in response to MyHCα." (PMID 33466825, 2021). "Adoptive transfer of CD4+ T cells induced myocarditis in the recipients even 12 weeks after rBCG-MyHCα immunization, which indicated that rBCG-MyHCα maintained the effector function of CD4+ T cells for extended periods of time." (PMID 33466825, 2021). "None-the-less, TREGS are generally thought to be cardioprotective during myocarditis while effector CD4+ T cells are critical players in myocarditis pathogenesis." (PMID 33483751, 2021). "In a transgenic mouse model expressing a MyHCα-specific T cell receptor on CD4+ T cells, myocarditis developed spontaneously, and the cooperation of IFN-γ and IL-17A was found to be essential for the transition from myocarditis to DCM." (PMID 33466825, 2021). "In EAM, CD4+ T cells induce the development of myocarditis, which is characterized by mononuclear macrophage infiltration, necrosis of cardiomyocytes, and proliferation of cardiac fibroblasts." (PMID 34497836, 2021). "Adoptive transfer of CD4+ T cells isolated from rBCG-MyHCα-immunized mice at 12 weeks after immunization successfully induced severe myocarditis in the recipient mice." (PMID 33466825, 2021). "We have previously shown that FoxP3- CD4+ T-lymphocytes significantly contribute to age-related myocardial inflammation in mice." (PMID 34046028, 2021). "Twenty studies included biopsy-verified myocarditis with findings of immune infiltration of the myocardium with CD4-positive T-lymphocytes, CD8-positive T-lymphocytes and CD68-positive macrophages." (PMID 34365980, 2021). "As they are an integral part in subacute and chronic phases, a better understanding of dysregulated CD4+ T cells in the pathogenesis of myocarditis is called for." (PMID 32269577, 2020). "The roles of CD4+ T cell subsets in myocarditis greatly depend on the interactions between the resident and infiltrating inflammatory cell types." (PMID 32269577, 2020). "In this review, we review myocarditis with an emphasis on its pathogenesis, and present a summary of current knowledge of dysregulated CD4+ T cells and miRNAs in myocarditis." (PMID 32269577, 2020). "Dysregulated CD4+ T cells and their related cytokines are critical for the development and progression of myocarditis." (PMID 32269577, 2020). "Myocarditis is the result of a combination of inflammatory cytokines, among which CD4+ Th17 cell-related cytokines play a major role in the disease." (PMID 33643041, 2020). "CD4+ T cells are key modulators in myocarditis, and the effector and regulatory subsets, respectively, promote and inhibit autoimmune responses." (PMID 32269577, 2020).
myocarditis (continued). "In this review, we provide a brief overview of myocarditis with an emphasis on its pathogenesis, and then summarize dysregulated CD4+ T cells subsets and the reciprocal interactions of these subsets in myocarditis." (PMID 32269577, 2020). "The depletion of CD4+ T-lymphocytes has shown reduced cytotoxicity in myocarditis and CD8+ T-lymphocytes activities." (PMID 32244307, 2020). "Since CD4+ T cells paly central roles in myocarditis and orchestrate the disease, they are a viable therapeutic target." (PMID 32269577, 2020). "Both dysregulated CD4+ T cells and miRNAs play critical roles in the pathogenesis of myocarditis, and the classic triphasic model of its pathogenesis consists of the acute infectious, subacute immune, and recovery/chronic myopathic phase." (PMID 32269577, 2020). "As miRNAs are involved in both the etiology and pathogenesis of myocarditis, we proceed to review the biogenesis and function of miRNAs, and discuss miRNAs that modulate CD4+ T cells." (PMID 32269577, 2020). "The observation that chronic inflammation and long-term antigen activation alters Teff responses supports our idea that a bystander activation of CD4+ T cell protects myocarditis patients from progression to heart failure." (PMID 31863205, 2019). "An increase in CD4+ T cells and mast cells during myocarditis following BPA exposure is consistent with the increased myocardial and pericardial inflammation observed with histology for the 5 μg BPA/kg BW dose." (PMID 31551929, 2019). "We assume that in myocarditis, mainly γc-cytokines produced by heart-specific CD4+ T cells promote the antigen-independent response of heart non-specific CD4+ T cells." (PMID 31863205, 2019). "Accordingly, our findings can potentially explain the difficulties in identifying heart-specific CD4+ T cells in human myocarditis." (PMID 31863205, 2019). "Previous reports on ICI-related myocarditis have shown that significant T cells (CD4+, CD8+) and macrophage infiltration were observed in the myocardium, cardiac conduction system, interventricular septum and pericardium." (PMID 31849640, 2019). "Histopathology confirms that myocarditis is a T cell-mediated immune response, mainly infiltrating myocardium by CD11b+ and CD4+ T cells." (PMID 32128091, 2019). "CD4+ and CD8+ T cells have been reported to be involved in the pathogenesis of myocarditis by many authors; however, regulatory T cells (Tregs), a subset of CD4+ T cells, have been shown to have protective effects." (PMID 29854842, 2018). "In this review, we will focus specifically on the regulatory role of different CD4+ T cell subtypes in general in the context of myocarditis and its progression to inflammatory dilated cardiomyopathy." (PMID 30035131, 2018). "Autoreactive, most often, infection-triggered CD4+ T cells were confirmed to be critical for myocarditis induction." (PMID 30035131, 2018). "Supporting the enhanced myocarditis, the number of CD4+ T-cells infiltrating the heart tissue of Pik3cg−/−-infected mice was increased compared to WT mice." (PMID 29666415, 2018). "Further studies in animal models, as well as in human tissue samples, will be required to fully understand the specific role of all different CD4+ T cell subsets in myocarditis." (PMID 30035131, 2018). "Transgenic mice carrying a CD4+ T cell receptor specific to cardiac myosin spontaneously develop myocarditis progressing to lethal-dilated cardiomyopathy." (PMID 30035131, 2018). "Many studies, most of them based on mouse models, indicate an exclusive role for CD4+ T cells in myocarditis development and progression." (PMID 30035131, 2018). "Effector CD4+ T cells (Teff) were reported to be critical for myocarditis development in patients and animal models." (PMID 30035131, 2018). "Aside from CD4+ T cell subsets including regulatory T cells (Treg), several other cell types can exert a regulatory suppressive function in myocarditis development." (PMID 30035131, 2018).
myocarditis (continued). "In the presence of tissue damage and innate immune activation, however, activated self-antigen-loaded dendritic cells promote CD4+ effector T cell expansion and myocarditis." (PMID 30035131, 2018). "MicroRNA-155 expression is up-regulated and localized primarily in heart-infiltrating macrophages and CD4(+) T lymphocytes during acute myocarditis." (PMID 29137434, 2017). "High rates of myocarditis are associated with CD4 counts of less than 400 cells/mm3 and up to two-thirds of untreated AIDS patients having histological evidence of myocarditis on autopsy." (PMID 26885518, 2016). "We found that microRNA-155 expression was upregulated and localized primarily in heart-infiltrating macrophages and CD4+ T lymphocytes during acute myocarditis." (PMID 26931072, 2016). "Further study about CD4+ T cells isolated from hearts of myocarditis patients by endomyocardial biopsy will be more valuable." (PMID 28018858, 2016). "Recent studies with an experimental murine model revealed not only the protective role of IL-10 against fatal myocarditis, but also demonstrated that this cytokine was produced by both CD4+ and CD8+ subsets of IFN-γ+IL-10+ double-producing T cells." (PMID 24901991, 2014). "Myocarditis, observed during both the acute and chronic phases of the disease, is characterized by an inflammatory mononuclear cell infiltrate that includes CD4+ T cells." (PMID 23776551, 2013). "The ability to image immune cells such as CD4+ T cells involved in autoimmune responses may enhance early diagnosis and monitoring of myocarditis." (PMID 40948965, 2025). "Moreover, CD4 + T cell responses, specifically, have the capacity to transform an initial myocarditis condition into an autoimmune reaction." (PMID 39075540, 2024). "Acacetin can regulate dysregulated CD4+ T cell responses in myocarditis." (PMID 38741130, 2024). "This is consistent with the previous trend in this study, so it can be hypothesized that there may be a link between an increase in the absolute CD39+ CD4+ T cell count and the onset or progression of myocarditis." (PMID 39280093, 2024). "Bbsl infected C57BL/6J (B6)‐Rag1 knockout mice, which lack T‐ and B cells, developed severe arthritis and myocarditis after reconstitution with either pan T cells or only CD4+ T cells, indicating a minor role for T cells in reducing the duration of active infection and the severity of LB." (PMID 39396370, 2024). "Additionally, the main triggers of ICI-myocarditis factors are activated CD4+ T-cells, which direct the differentiation of CD4+ T-cells into Th17 effector cells and are vital in establishing the inflammatory process that results in myocardial tissue injury." (PMID 38236243, 2024). "Taken together, the transgenic system described in this report may be a helpful tool to distinguish the roles of cytotoxic cardiac antigen-specific CD4+ T cells vs. those of CD8+ T cells in the pathogenesis of myocarditis." (PMID 38334626, 2024). "In murine models, it has been shown that CD4+ T cells were the primary mediators of myocarditis." (PMID 39396370, 2024). "CD4+ T cells play a role in acute Parvovirus B19V-related myocarditis." (PMID 38464847, 2024). "Furthermore, flow cytometric analysis of CD4+ T cells in isolated cardiac inflammatory cells indicated that LIPUS significantly increased the Treg cell infiltration in the myocarditis heart." (PMID 37069636, 2023). "A vaccine-induced activation of the immune system in persons with otherwise peripheral tolerance due to regulatory T cells might promote CD4 + effector T cell expansion and myocarditis." (PMID 36436002, 2023). "CD4+ T cells have been previously shown to play a significant role in the CVB3-induced myocarditis." (PMID 37669302, 2023). "Indeed, histopathological samples from patients with ICI myocarditis revealed increased myocardial infiltration of T-lymphocytes (both CD4 and CD8) and macrophages." (PMID 36979163, 2023).
myocarditis (continued). "It has been established that activated antigen‐specific T lymphocytes play an important role in the pathogenesis of myocarditis, and a mouse model of experimental autoimmune myocarditis (EAM) has been developed to mimic the immune responses associated with heart‐specific CD4+ T cells." (PMID 37382257, 2023). "In co-infected patients, the reactivation of Chagas disease is related to their high parasite load, high HIV viral load, and CD4 T-cell counting less than 200/mm3, which may evolve to meningoencephalitis and myocarditis." (PMID 35353834, 2022). "CD4+helper T-cells are critical drivers in cardiomyopathy and myocarditis pathogenesis." (PMID 35926050, 2022). "The pathogenesis of EAM and myocarditis involves multiple arms of the innate and adaptive immune response, with CD4+ T cells, i.e., T helper (Th) cells and macrophages playing the dominant pathogenic role, and regulatory T cells (Treg) having a major anti-inflammatory role." (PMID 34944410, 2021). "Similarly, in the context of myocarditis, CD4+ T cells have been shown to drive CD8+ T cell trafficking through the release of IL-2116." (PMID 33674611, 2021). "However, exposure for 2 weeks to 250 μg BPA/L (50 BPA) in drinking water significantly increased the expression of CD3 (p = 0.007) and CD4 (p = 0.02) in the heart compared to the 0 BPA control water (glass) during CVB3 myocarditis in the males." (PMID 34445539, 2021). "Depletion of CD8+ cells from these CD4 KO mice ameliorated the CD4 KO-induced increase in myocarditis, suggesting that CD4+ T cells may limit cardiac damage in part by suppressing the activity of cytotoxic T cells." (PMID 34696354, 2021). "Furthermore, the transfer of cTnI-specific CD4+ effector T cells to healthy recipients causes severe inflammation, fibrosis, and cardiac dysfunction in animal models, suggesting an exclusive role for CD4+ T cells in myocarditis development and progression." (PMID 34307494, 2021). "In addition, reciprocal regulation of CD4+ T cell subsets is also important in the pathogenesis of myocarditis." (PMID 32269577, 2020). "Furthermore, the reciprocal interplay of these subsets influences the pathogenesis of myocarditis as well, and roles of dysregulated miRNAs modulating CD4+ T cells in the pathogenesis of myocarditis have gained attention recently." (PMID 32269577, 2020). "Based on clinical and animal data, the classic triphasic model of pathogenesis of myocarditis was proposed, which consists of the acute infectious, subacute immune, and recovery/chronic myopathic phase, and both dysregulated CD4+ T cells and miRNAs play critical roles." (PMID 32269577, 2020). "The bias of CD4+ Th immune response greatly affects the severity of myocarditis." (PMID 32220054, 2020). "Analysis of peripheral CD4+ T cells in a patient with acute myocarditis demonstrated that Th1 was dominant during the acute phase and coincided with increased serum levels of creatine kinase (CK), while Th2 predominated during the recovery phase and was accompanied by decreased CK levels." (PMID 32269577, 2020). "Dysregulated CD4+ T cells in the pathogenesis of myocarditis." (PMID 32269577, 2020). "Therefore, analyzing dysregulated miRNAs together with their mRNA and protein targets in heart biopsies and body fluids offer an opportunity to find potential therapeutic targets, though the crosstalk between miRNAs and CD4+ T cells in myocarditis is elusive." (PMID 32269577, 2020). "In the infectious model, myocarditis is triggered by the immune response to the virus infecting and replicating in cardiomyocytes, whereas in the autoimmune model, myocarditis is mainly mediated by the activated heart-specific CD4+ T lymphocytes." (PMID 33053859, 2020). "Furthermore, adoptive transfer experiments demonstrated that heart-specific CD4+ T cell mediated myocarditis induction paralleled a strong bystander activation of heart non-specific CD4+ T cells." (PMID 31863205, 2019).
myocarditis (continued). "Furthermore, we demonstrated Teff phenotype of heart infiltrating CD4+ T cells also in human myocarditis." (PMID 31863205, 2019). "More than 80% of donor CD45.1+CD4+ cells displayed Teff phenotype and these cells effectively accumulated in the hearts of the recipients, confirming the potential of heart-reactive Teff to trigger myocarditis." (PMID 31863205, 2019). "In contrast, heart-reactive TCR-M Teff (which express CD90.1 alloantigen) efficiently accumulated in the recipient hearts after adoptive transfer, although they induced myocarditis less efficiently than CD45.1+CD4+ T cells obtained from α-MyHC/CFA immunized mice." (PMID 31863205, 2019). "Antigen-specific responses of α-MyHC-reactive CD4+ T cells are crucial for myocarditis induction." (PMID 31863205, 2019). "Whether or not these in vitro findings are relevant during viral myocarditis needs further investigation—a challenging task given the relatively weak IL-17 signal obtained from CD4+ T cells during acute myocarditis." (PMID 30546359, 2018). "Interestingly, recent observations point out that various CD4+ T cell subsets demonstrate high plasticity in maintaining immune homeostasis and modulating disease phenotypes in myocarditis." (PMID 30035131, 2018). "So far, a direct pathogenic role has been described for both activated Th17 and Th1 effector CD4+ T cell subsets, though Th1 effector T cell-derived interferon-gamma was shown to limit myocarditis severity and prevent transition to inflammatory dilated cardiomyopathy." (PMID 30035131, 2018). "Consistently, adoptive transfer of female- but not male-derived M-MDSCs efficiently alleviated CVB3-induced myocarditis in male recipient mice, and this protection could be ascribed to the increased induction of regulatory and CD4+IL-10+ T cells." (PMID 26939768, 2016). "The severity of myocarditis is largely influenced by the bias of CD4+ Th immune response." (PMID 26931072, 2016). "Subsequently, this effect could be beneficial in the subacute stage of myocarditis, preventing the induction of a second wave of immune cell infiltration, including antigen-specific CD4+ and CD8+ T lymphocytes." (PMID 23853610, 2013). "In addition, it has been reported that the adoptive transfer of myosin-specific CD4+ Th17 cells induces autoimmune myocarditis in normal mice, which demonstrates a crucial role for Th17 cells in the immune mechanism of myocarditis onset." (PMID 23977238, 2013). "CD8+ T-cells-enriched myocarditis persisted at 90 dpi (R1 gate: 47.6–73.6% TCRαβ+: 17.3–19.4% TCR TCRαβ+CD4+vs. 28.2–51% TCR TCRαβ+CD8+, two independent experiments) when the highest level of CK-MB activity in the serum, demarking the cardiomyocyte lesion, was detected." (PMID 22532799, 2012). "It has also been reported that IFNγ acts as a positive regulator of CD25 expression on CD4+ T cells in a mouse model of myocarditis, though it is unclear whether IFNγ directly or indirectly controls CD25 expression in CD4+ T cells." (PMID 21731484, 2011). "Besides, because both IFN-γ+ and IL-17+ CD4+ T cells can be detected in diseased mice, Is myocarditis a simple Th1 or Th17 driven disease, or there is considerable overlap between the developmental pathways that produce IFN-γ+ and IL-17+ effector cells?" (PMID 21672246, 2011). "Low-intensity pulsed ultrasound (LIPUS) can limit inflammatory responses, with positive therapeutic effects across various cardiovascular inflammatory diseases; however, its role in the pathogenesis of ICI-related myocarditis and CD4+ T-cell dysfunction remains unclear." (PMID 38236243, 2024). "Therefore, targeting CD4+ T cell activation may be crucial for developing new treatment of myocarditis." (PMID 38741130, 2024). "Acacetin may be a valuable therapeutic drug in treating CD4+ T cell-mediated myocarditis." (PMID 38741130, 2024).